CXCR4 (C-X-C motif chemokine receptor 4)
Diseases named in the same sentence as CXCR4 in open-access papers (continued):
Sharing a sentence is not in itself a finding about the gene and the disease.
tumor (continued). "Moreover, we analyze the most recent data on the role of GPCRs in regulating tumor angiogenesis, particularly focusing on the role of chemokine receptor CXCR4 and the G-protein estrogen receptor (GPER) (Section 3)." (PMID 29240722, 2017). "Strong CXCR4 positivity was also seen in tumor-infiltrating lymphocytes." (PMID 29282035, 2017). "Our findings suggest that miR-302b may be a novel CRI regulating miRNA that inhibits CRI critical pathway and downstream cytokines expression through targeting ERBB4, IRF2 and CXCR4, resulting in decrease of tumor growth." (PMID 28467773, 2017). "We investigated the pharmacokinetics of N-[11C]methyl-AMD3465 in rats bearing a C6 tumor and assessed whether the CXCR4 occupancy by the drug Plerixafor® can be measured with this PET tracer." (PMID 27896627, 2017). "As for the combination of CXCR4 and CXCL12 levels, CXCR4high/CXCL12high in GC is significantly associated with tumor invasion depth, LN involvement, and higher TNM stage, which causes the worst prognosis, whereas patients with CXCR4low/CXCL12low show the best prognosis." (PMID 28544785, 2017). "The CXCR4+ tumor tissue H-score mean was 203.0 with a median of 200.0." (PMID 28299514, 2017). "Furthermore, CXCL12 can attract CXCR4-positive immune cells or fibroblasts to the tumor sites to assist in tumor development." (PMID 28566721, 2017). "CXCR4 is also a key regulator of the EMT process, through which it could activate signals associated with tumor progression." (PMID 28415580, 2017). "Therefore, designing a new CXCR4 antagonist to prevent tumor metastasis will be of great significance." (PMID 28793338, 2017). "Moreover, the enhanced intracellular uptake of CTCE-NPs was observed, indicating that NPs presenting a CXCR4 antagonist CTCE9908 peptide can increase tumor uptake in the murine HCC model." (PMID 28276530, 2017). "Importantly, miR-125b was upregulated by the activation of CXCL12/CXCR4 axis, and then miR-125b in turn enhanced the expression of CXCR4, which forms a positive feedback loop in triggering tumor invasion and progression." (PMID 28176874, 2017). "Our data suggested that chemotherapy could establish drug-resistant and tumor-initiating properties of OVC via reversible CXCR4 cell state transition." (PMID 28196146, 2017). "Although CXCR4 is mutagenic for PC and other tumor cells, a recent study demonstrated that CXCR4 could also amplify the metastatic state of PC cells." (PMID 27974694, 2017). "Staining a multi-cancer/multi-tumor array identified ACC expressing high levels of CXCR4." (PMID 29088715, 2017). "CXCR4 participates in the development of heart and blood vessels, the generation of hematopoietic cells, and the immune response in the biological process, also being involved in adjusting the malignant tumor growth and metastasis." (PMID 28293639, 2017). "Activation of Cxcl12/Cxcr4 signaling appears to be needed for antral tumor growth." (PMID 29340033, 2017). "Inspired by the significant inhibitory effect of E5 on AML, we applied E5 on overexpressed-CXCR4 solid tumor cells, and investigated whether E5 could sensitize tumor cells to chemotherapeutics." (PMID 28793338, 2017). "Furthermore, through encapsulation of chemotherapeutic drug doxorubicin (Dox) into M-E5, we found that M-E5 was capable of sensitizing tumor cells for Dox in vitro via blocking CXCR4/CXCL12 axis." (PMID 28793338, 2017). "Accordingly, inhibition of CXCR7 function may serve to increase the clinical efficacy of CXCR4 inhibitors such as AMD3100, as blockage of CXCR4 only partially inhibits tumor cell response to CXCL12 gradients in multiple animal models." (PMID 28055968, 2017). "Variable CXCR4 levels between testis tumor samples suggested responsiveness to CXCL12 may differ between individuals." (PMID 29250030, 2017). "MIF secreted from tumor cells attracts MSCs to the lungs in CXCR4-dependent manner." (PMID 28798777, 2017).
tumor (continued). "Therefore, the simultaneous inhibition of HER2 and CXCR4 by AAPC treatment enhanced its anti-tumor and anti-metastatic effects." (PMID 28405006, 2017). "Because CXCL12 is the target molecule of HIF-1α, the hypoxic condition resulting from bevacizumab treatment could lead the tumor cells to produce CXCL12, which would in turn prompt the CXCR4+ cells to migrate into the tumor." (PMID 29286323, 2017). "In both HCC and CCC, indirect targeting of tumors via the CXCR4-positive tumor capillaries may represent a promising additional therapeutic strategy." (PMID 29282035, 2017). "As the CXCR4 signaling pathway have a stimulating role in the main processes of the TME in many tumor types, CXCR4 could be a candidate biomarker and a potential therapeutic target." (PMID 28549419, 2017). "On the other hand, the activation of CXCR4 signaling pathway could enhance the infiltration and attacking ability of hepatic malignant tumor cells and then induce the transfer of cancer cells." (PMID 28293639, 2017). "High expression of CXCL12/CXCR4 was observed in all passages of both tumours and in the neovascularisation experiment, this could be related with their aggressive clinical behaviour." (PMID 28386296, 2017). "Another important function of C/EBP transcription factors is to regulate gene expression, such as VEGFR3 in lymphatic endothelial cells, platelet-derived growth factor receptor in vascular smooth muscle cells, insulin-like growth factor-I in osteoblast cells, and CXCR4 in tumor cells." (PMID 28881585, 2017). "For example, inhibition of CXCR4 reduced the microglial chemotaxis towards the tumor cells." (PMID 28008153, 2017). "CXCR4 expression on tumor cells is indicated to be correlated with a poor prognosis in cancer patients, which may be involved in the chemosensitivity of cancer cells." (PMID 29117108, 2017). "Furthermore, gelatin zymography analysis has demonstrated that SIK3 induced expression of tumor metastatic CXCR4 through MMP-9 activation." (PMID 28658303, 2017). "Thus, we draw that QRHX played a more important role in inhibiting tumor growth by regulating TAMs in mice, which was found to be associated with the inhibition of inflammation and the CXCL12/CXCR4/JAK2/STAT3 signaling pathway." (PMID 28630636, 2017). "In addition to Hh signaling, we found a potent effect of honokiol against C-X-C chemokine receptor type 4 (CXCR4), another important factor that mediates tumor-stromal cross-talk." (PMID 28273819, 2017). "Our studies showed that, encapsulating E5 in PEG-PE micelle could enhance the binding ability of E5 for CXCR4-overexpressing tumor cells that prevent the tumor cells motility." (PMID 28793338, 2017). "Here, we show that tumor xenograft derived from cellular suspension of larger tumors with higher CXCR4 generated under the first bevacizumab treatment was less responsive to the subsequent treatment with bevacizumab and grown much more of tumor originated from smaller tumors with lower CXCR4." (PMID 28057017, 2017). "The xenograft residual PC model utilized in the present study, coupled with the achievability of tumor-specific RT, allowed us to define such function-focused molecular events in PC and recognized the critical role of two candidates, CXCR4 and COX2, in this setting." (PMID 27974694, 2017). "However, tumor accumulation (13.1 ± 1.5% ID/g, 1.5 h p.i.)was CXCR4-specific and higher than in all other organs and resulted in high resolution delineation of Daudi tumors in PET/CT images in vivo." (PMID 29527563, 2017). "As expected, there were significantly higher volumes of subcutaneous tumors in the MIF group compared to the other groups, indicating that in vivo, MIF contributes to tumor progression and could be inhibited by blocking CXCR4-AKT pathway activity." (PMID 29113309, 2017). "We found that CXCR4 was intensely expressed on tumor vessels in about 50% of both HCCs and CCCs." (PMID 29282035, 2017).
tumor (continued). "Moreover, overall survival of patients with HCC was significantly lower when CXCR4-positive tumor capillaries were present (log-rank test: p = 0.020)." (PMID 29282035, 2017). "In addition, more CXCR4-overexpressing MSCs accumulated in the tumor than non-CXCR4-overexpressing MSCs." (PMID 28740515, 2017). "It has been illustrated that the SDF-1/CXCR4 axis could promote the expression of smoothened, a vital protein in the Hh pathway whose overexpression can induce tumor cell EMT and invasion." (PMID 29254283, 2017). "This gradient may attract CXCR4 positive tumor cells to the endothelium approaching the vasculature." (PMID 28785589, 2017). "Deletion of the JunD gene in the stroma promoted tumor growth and metastasis, associated with increased ROS production, with consequent accumulation of HIF1α and HIF1α-dependent induction of CXCL12, activating CXCR4, promoting CAF differentiation." (PMID 29137220, 2017). "To identify whether HT-EA affects PC cell dissemination destiny by selectively targeting CXCR4/COX2, we assessed the alterations in tumor cell migration and invasion after ectopic expression of CXCR4/COX2 in PANC-1 and MiaPaCa-2 cells treated with HT-EA." (PMID 27974694, 2017). "While Cxcr4+ epithelial cells are normally at the gland base surrounded by Cxcl12+ endothelial cells, there was marked expansion of Cxcr4+ epithelial cells to within the antral tumor." (PMID 29340033, 2017). "Particularly in OVC, silencing CXCR4 expression by siRNA reduces tumor growth." (PMID 28196146, 2017). "The tumor-surrounding “normal” liver tissues were largely devoid of any SSTR or CXCR4 expression." (PMID 29282035, 2017). "We demonstrate here that CXCR4 signaling, which increases PDGFRα activity, could enhance tumor invasion ability." (PMID 28415580, 2017). "Additionally, the VHL tumor suppressor gene inhibits the expression of the chemokine receptor type 4 (CXCR4) by degrading HIF, which promotes transcription of CXCR4." (PMID 28796163, 2017). "Moreover, CXCR4 expression is increased in a variety of human cancers where it regulates tumor progression and EMT." (PMID 28774348, 2017). "Mechanistic studies implied that E5 can inhibit the expression of CXCR4 to block the CXCL12-mediated recruitment of endothelial progenitor cells and repress CXCR4 downstream of the Akt and Erk signaling pathway, which are involved in tumor angiogenesis and progression." (PMID 29263923, 2017). "However, CXCR4 knockdown attenuated the effect of CXCL12 on enhancing tumor spheroid formation in HBx-expressing OV6+ CSCs." (PMID 28102846, 2017). "Recently, it was shown that CXCR4 GSC are attracted to the perivascular space and transforming growth factor beta (TGF-β) expressed by endothelial cells canguide the differentiation of CXCR4 expressing GSC into mature pericytes to support tumour vascular sprouting and further growth." (PMID 29113105, 2017). "In contrast, CXCR4 silencing leads to inhibition of tumor growth and to reduced survival." (PMID 28774348, 2017). "Due to the critical role of SDF-1/CXCR4 interaction in immune cell retention and mobilization, CXCR4 inhibition may lead to T-cell infiltration and redistribution in tumor microenvironments." (PMID 29212254, 2017). "Tumor sections were stained with a-CXCR4/AlexaFluor488 and DAPI." (PMID 28566721, 2017). "Indeed, we observed a slight upregulation of both CCR7 and CXCR4, essential receptors required for LN trafficking of DCs, upon loss of MK2 in tumour-infiltrating DCs." (PMID 28924177, 2017). "Moreover, the inability of NK cells to traffic to tumor sites has been eliminated by the addition of C-X-X motif chemokine receptor 4 (CXCR4) in the CAR construct." (PMID 28850071, 2017). "In both HCC and CCC, indirect targeting of the tumors via the CXCR4 expressed on the tumor capillaries may represent an additional promising therapeutic strategy." (PMID 29282035, 2017). "CXCL12/CXCR4 signaling axis regulates the process of tumor proliferation and metastasis." (PMID 28489887, 2017).
tumor (continued). "Only faint tumor CXCR4 expression was shown by IHC (immuno reactive score of 3)." (PMID 29221153, 2017). "Therefore, in this study, we evaluated the efficacy of an intravenous infusion of genetically engineered mesenchymal stem cells (MSCs) overexpressing CXC chemokine receptor 4 (CXCR4) to home to the tumor, by optical imaging." (PMID 28740515, 2017). "Interestingly, there are strong Cxcr4-GFP expressing clusters within the tumor, suggesting the clonal expansion of Cxcr4+ cells in dysplastic glands." (PMID 29340033, 2017). "In addition, we evaluated the correlation of baseline CXCR4 expression in tumor tissue and in CTCs from patients in this phase II study." (PMID 28299514, 2017). "In line with this, blocking CXCR4 results in inhibition of tumor metastasis." (PMID 27307990, 2016). "In addition, we detected a direct correlation between tumor size and CXCR4 expression at the time of necropsy." (PMID 27528222, 2016). "In human colon cancer, CXCR4 is overexpressed in the chemoresistant tumor cells." (PMID 27270649, 2016). "In addition to hematological tumor cells, CXCR4 inhibition has also been reported to induce apoptosis in many other tumor cells." (PMID 26954567, 2016). "Our findings provide further evidence for the mechanism of CXCL12/CXCR4-mediated cellular proliferation, leading to novel therapeutic strategies to prevent tumor progression that may bring CXCL12/CXCR4-targeted therapy closer to clinical reality." (PMID 27439769, 2016). "Furthermore, CXCR7 can also influence CXCR4-mediated chemotaxis and invasion, as well as independently regulate tumor growth by promoting angiogenesis." (PMID 27049755, 2016). "The expression of the chemokine receptor CXCR4 was found to be higher in cells from tumor thrombus than paired cancer tissues as well as on CSQT-2, which may explain the development of PVTT in the portal vein." (PMID 27027235, 2016). "Nevertheless, we used CD49f together with CXCR4 to analyze heterogeneity of tumor cells." (PMID 26385771, 2016). "Alternatively, the positive correlation between CXCR4 expression and tumor size might be due to the direct impact of CXCR4 signaling on tumor growth." (PMID 27528222, 2016). "The association between BM and mutation in PIK3CA and BRAF, expression of NCAM, EGFR, and CXCR4, MGMT methylation and increase in the tumor marker CA19.9 have also been investigated, but only in one or two studies each and on small samples, so the possible predictive potential is hard to determine." (PMID 27037031, 2016). "Our findings demonstrate knocking down CXCR4 significantly increases mice's overall median survival, reduces tumor migration and invasiveness along brain endothelial cells and increases the sensitivity of tumor cells to radiation therapy." (PMID 27863376, 2016). "Hence, from this study it can be inferred that therapy using CXCR4 inhibitor should be concentrated on mesenchymal GBM patients who have tumor cells dependent on CXCR4 axis." (PMID 27382437, 2016). "In addition, previous studies showed that CAFs secrete SDF-1, activate SDF-1/CXCR4 axis, and promote tumor progression." (PMID 26851944, 2016). "Therefore, tumor specificity is achieved by placing the E1A gene under transcriptional regulation of a tumor specific promoter, CXCR4 in breast cancer and prostate specific antigen (PSA) promoter in prostate cancer." (PMID 27494901, 2016). "Stromal cells release CXCL12 and attract CXCR4-expressing tumor cells to the new microenvironment." (PMID 27835905, 2016). "CXCL12/CXCR4 axis plays a crucial role in determining the homing of metastatic tumor cells with poor prognosis, which the expression of CXCR4 and Bcl-2 and PI3K/Akt and ERK1/2 signaling are controlled and the level at which it is expressed mark the difference between normal and pathological events." (PMID 27668882, 2016). "The CXCR4 antagonist IT1t has promising tumor inhibitory effects." (PMID 26744352, 2016).
tumor (continued). "Furthermore, it is worth recalling data from others that suggest the role of CD133 and CXCR4 content in sustaining high metastatic capacity in in vitro and in vivo model of some tumor types." (PMID 26897742, 2016). "Based on our present results, we suggest that serum CXCR4 may improve the diagnosis of EC patients, especially in combination with classical tumor markers." (PMID 27041792, 2016). "In the current study, we investigated plasticity of CXCR4 expression in vivo and assessed whether CXCR4 impacts on tumor growth." (PMID 27528222, 2016). "Moreover, the tumor mass formed by Lgr5+/CXCR4+ cells was significantly greater than tumor mass from the other cell populations." (PMID 27835894, 2016). "It has been reported that high CXCL12 levels in the tumor may attract CXCR4-positive vascular and inflammatory cells that, once within the tumor, secrete tumor promoting cytokines as well as growth and pro-angiogenic factors." (PMID 27015814, 2016). "In the current study, we further defined the mechanisms involved in B cell-mediated killing of tumor cells and found that activated B effector cells killed tumor involving the CXCR4/CXCL12 and perforin pathways as well as the Fas/FasL interaction, and can be augmented by IL-2." (PMID 27528023, 2016). "Since CXCR4 expression is involved in primary tumor growth, tumor invasiveness, metastasis, angiogenesis and vasculogenesis, this subpopulation of CXCR4 overexpressing cells can be targeted by CXCR4 inhibitors." (PMID 26920352, 2016). "Therefore, there is increasing evidence that CXCL12 and its specific receptor CXCR4 play an important role in many steps of tumor progression, such as invasion, migration, and proliferation of malignant cells." (PMID 27041792, 2016). "Moreover, resveratrol downregulated nuclear localization of NF-κB, NF-κB phosphorylation and its acetylation, causing attenuation of NF-κB-regulated gene products (MMP-9, CXCR4) involved in tumor-invasion and metastasis." (PMID 26959057, 2016). "We propose that similar to in vitro data, in vivo GemOE cells recruit MSCs to their vicinity through secreting Ac-HMGB1 that promotes expression and activation of RAGE, which in turn induces CXCR4 expression in MSCs that responds to high levels of SDF1 secreted from GemOE tumor cells." (PMID 26989079, 2016). "Additionally, CXCR4 is significantly related to the biological features of the tumor stage, including stage, Fuhrman grade, and clinical presentation." (PMID 27293448, 2016). "Examination of gene expression in the excised tumors revealed that CXCR4 transcript levels in resected tumors directly correlated with tumor volume, suggesting that expression of CXCR4 in established tumors might promote tumor growth." (PMID 27528222, 2016). "In addition, several factors and organ microenvironments have been shown to regulate CXCR4 expression in tumor cells." (PMID 27809841, 2016). "To directly assess the role of Ac-HMGB1 secreted from GemOE tumor cells on induction of CXCR4 on the surface of MSCs, we again exposed early passage MSCs for 24 h to fresh HME medium supplemented or not with recombinant HMGB1 (rHMGB1, 10 μg/ml) that was in vitro acetylated." (PMID 26989079, 2016). "Thus, it is imperative to identify the mechanism by which the expression and/or activation of FAK and CXCR4 is induced specifically in tumor cells." (PMID 26993780, 2016). "CXCR4 is known to be expressed on some tumor cells, which may metastasize to the organs that secrete/express SDF-1." (PMID 27835894, 2016). "Thus, 20 tumor cells isolated from either control, CXCR4+/Lgr5-, Lgr5+/CXCR4- or Lgr5+/CXCR4+ cells were transplanted s.c. into new NOD/SCID mice." (PMID 27835894, 2016). "Indeed, unexpectedly, we found a significant upregulation of CXCR4 expression, and a sensible increase of cell migration indicating an enhanced tumor tropism of Au enriched cells." (PMID 27223433, 2016).